PXN (paxillin)
Diseases named in the same sentence as PXN in open-access papers (continued):
Sharing a sentence is not in itself a finding about the gene and the disease.
tumor (continued). "To compare expression levels of the PXN gene between tumor and normal tissues, we obtained expression of PXN across various cancer types in TCGA dataset via the TIMER2 tool." (PMID 34135128, 2021). "Given the crucial role of PXN in tumorigenesis, we conducted a pan-cancer analysis of PXN expression and patient prognoses via TCGA, the Clinical Proteomic Tumor Analysis Consortium (CPTAC), the Human Protein Atlas (HPA) cohort, and GEO databases." (PMID 34135128, 2021). "The FAK/paxillin signaling pathway, downstream of integrin αv, is involved in tumor progression, angiogenesis, and metastasis." (PMID 33834020, 2021). "To assess the tumor-promoting effect of PXN in HNSCC cells, we performed knockdown assays using siRNAs." (PMID 34946859, 2021). "The knockout of PTPRT dephosphorylates PXN at Tyr38, which results in a marked increase in tumor size in the APCmin+/− mice." (PMID 32456226, 2020). "The results indicated that paxillin promoted Bcl-2 activation by mediating ERK activation, which was associated with tumor formation efficacy in mice." (PMID 32849902, 2020). "These authors reported co-localization of paxillin in auto phagosomes in metastatic tumor cells, indicating that paxillin is degraded via autophagy, favoring the disassembly of FA and cell motility." (PMID 33117715, 2020). "We found that LIPH silencing significantly attenuated adhesion between tumour cells by modulating the FAK p397‐paxillin signalling axis in MDA‐MB‐231 cells." (PMID 32618099, 2020). "Autophagy promotes focal adhesion disassembly and cell motility of metastatic tumor cells through the direct interaction of Paxillin to LC337." (PMID 33004792, 2020). "PEAK1 promotes cell proliferation, migration, and tumor growth by activating paxillin (PXN), p130Cas and ERK." (PMID 32456226, 2020). "This is the first report that PXN is directly regulated by tumor-suppressive miR-139-3p in RCC cells." (PMID 33322675, 2020). "In macrophages, miR-375 directly targets TNS3 and PXN to enhance macrophage migration and infiltration into tumor spheroids and in tumors of a xenograft mouse model." (PMID 30850595, 2019). "For instance, paxillin, which is a multi-domain adaptor protein, is involved in essential processes such as embryonic development, wound repair, and tumor metastasis by binding to various signaling proteins associated with actin cytoskeleton organization." (PMID 31269666, 2019). "Our work adds to a growing body of work linking SEPT9, F-actin, microtubules and FAs to tumor cell motility, migration, and metastasis, especially the link between SEPT9_i1 and paxillin was first suggested by IF and COIP analysis." (PMID 31558699, 2019). "Collectively, these data suggest that tumor-derived miR-375 increased MΦ migration by downregulating the migration inhibitory proteins PXN and TNS3 in MΦ." (PMID 30850595, 2019). "The impact of this inhibitor on the phosphorylation of FAK and on the expression of its downstream effector paxillin in tumor cells was than investigated." (PMID 30717801, 2019). "Soluble tumor-derived factors, including vascular endothelial growth factor, decrease PXN expression in capillary endothelial cells." (PMID 30850595, 2019). "Both ways are effective to rescue the paxillin level, indicating potential drug targets for tumor metastasis." (PMID 30200999, 2018). "For example, the direct neurofibromin 2-paxillin interaction has been shown to be involved in the stabilization of neurofibromin 2 at the plasma membrane, which is important for its tumor-suppressive functions." (PMID 29626191, 2018). "We also investigated several reported PTK6 substrate candidates that link PTK6 kinase to oncogenic signaling in tumor cells, including Akt, Paxillin, STAT3/5, ERK1/2, p38, FAK and p130CAS." (PMID 29879184, 2018). "Recent studies have demonstrated that the overexpression of paxillin at the RNA and protein level is associated with GBM tumor malignancy and hence, predictive of poor survival." (PMID 28214467, 2017).
tumor (continued). "Paxillin is an adapter protein involved in tumor growth, focal adhesion turnover, cell migration and metastasis." (PMID 27447856, 2017). "Recent work in colon cancer cells has shown that PTEN function as a tumor suppressor derives from the downregulation of paxillin expression by the inhibition of PI3K/AKT/NF-kB signaling." (PMID 28214467, 2017). "We discovered a novel binding site for STAT3 in the PXN gene promoter, which is responsible for tumor angiogenesis inhibition by nobiletin." (PMID 28468300, 2017). "To show SRC signaling is activated, we found phosphorylation of paxillin is upregulated suggesting tumor progression." (PMID 28396832, 2017). "FAK can regulate tumor angiogenesis as well as cell survival by forming a complex with Src through phosphorylation of paxillin (PXN)." (PMID 28468300, 2017). "PXN is a focal adhesion–related protein that interacts with the Src–FAK complex during tumor angiogenesis." (PMID 28468300, 2017). "Consistent with our initial report, we again observed strong pY88 paxillin staining in tumor tissue." (PMID 27447856, 2017). "With a VEGF inducer and inhibitor, however, we showed that nobiletin inhibited tumor angiogenesis by regulating Src/FAK/STAT3 through PXN." (PMID 28468300, 2017). "To further test the influence of TNC on tumour metastasis-related genes, we examined the expression of Paxillin, p-PaxillinS178 and FAK." (PMID 29088796, 2017). "Paxillin and its relative Hic-5 appear to play a key role in invadopodia, which are cell protrusions that aid tumor metastasis." (PMID 26980710, 2016). "When nuclear expression of Lyn and Paxillin were entered into multivariate cox regression model with tumour stage, tumour grade and recurrence high membrane Lyn expression (p = 0.011) was demonstrated to be independent of other factors in the model." (PMID 26984511, 2016). "It is noteworthy that our study demonstrated that activation of the MRTF-dependent transcriptional pathway resulted in FAK activation and increased paxillin phosphorylation in various tumor cells." (PMID 27708220, 2016). "FAK signaling has been shown to regulate proteins (e.g. SRC, SYK, FYN, LYN, GRB2, PI3K, and paxillin) that are involved in modulating cytoskeleton rearrangements to enhance tumor growth and metastasis." (PMID 27472394, 2016). "The increased signal intensities and clustered peripheral distribution of pY397-FAK and pY118-paxillin were also observed in CA-MRTF-A-expressing tumor cells." (PMID 27708220, 2016). "Western blotting analysis showed that CA-MRTF-A expression also up-regulated the expression of FA proteins and increased phosphorylation levels of FAK and paxillin in these tumor cells." (PMID 27708220, 2016). "In the pilot study using Western blot analysis, about 40.7% of the HCCs exhibited significant elevation of PXN(p-Y31) in tumor tissues, compared with that in the normal counterpart." (PMID 26416447, 2015). "In spite of these discrepancies, Hic-5 was also capable of triggering tumor progression as paxillin, although via distinct molecular pathways." (PMID 26416447, 2015). "By inducing dephosphorylation of paxillin, PKCζ was responsible for NaL-C6-mediated stress fiber depolymerization and focal adhesion disassembly in the metastatic tumor cells." (PMID 25792190, 2015). "In the present study, phosphorylation of PXN at Y31/118 is required for tumor invasion via increased Bcl-2 expression." (PMID 25826088, 2015). "In tumor cells, paxillin is highly phosphorylated at Tyr118 and recruits other signalling molecules to focal adhesions for tumor metastasis." (PMID 24605059, 2014). "We further investigated the role of PXN on the tumor cell growth and proliferation through gain-of-function and loss-of-function analysis." (PMID 24180516, 2013). "It was reported that cell surface molecule such as CD24 mediates c-Src kinase for FAK phosphorylation and paxillin which in turn promote integrin-dependent adhesion and tumor cell invasion and metastasis." (PMID 23970932, 2013).
tumor (continued). "Paxillin (PXN) has been found to be aberrantly regulated in various malignancies and involved in tumor growth and invasion." (PMID 24180516, 2013). "TGase-4 was found to co-precipitate and co-localise with focal adhesion kinase (FAK) and paxillin, in cells, human prostate tissues and tumour xenografts." (PMID 24161123, 2013). "FAKpY925 has been shown to be critical for association with paxillin and Erk activation leading to metastasis and MAPK-associated angiogenesis mediated tumor progression through VEGFR." (PMID 23826330, 2013). "In this study, we detected the PXN mRNA and protein level in 30 paired tumor tissues and adjacent normal tissues and found that PXN was frequently up-regulated in tumor tissues." (PMID 24180516, 2013). "The CD24 mediates c-Src kinase for FAK phosphorylation and paxillin which in turn promote integrin-dependent adhesion and tumor cell invasion and metastasis." (PMID 23970932, 2013). "Here, we observed an interesting pattern in which both total FAK and total Paxillin were positively stained in the tumour cells in control tumours and in TGase-4 expressing tumours." (PMID 24161123, 2013). "High expression of paxillin was positively correlated with poor tumor differentiation, cervical lymph node metastasis and advanced clinical stage (III+IV)." (PMID 23209815, 2012). "Increased mutant A127T paxillin expression conferred cell growth, oncogenic transformation, and tumor growth and invasion in a nude mouse model." (PMID 23209815, 2012). "Two studies of HNSCC cell lines (UMSCC-1 and SCC 25) indicated that paxillin overexpression contributed to increasing adhesion ability and that paxillin downregulation played a role in suppressing tumor cell proliferation and angiogenesis." (PMID 23209815, 2012). "In contrast, these equivalent phospho-cofilin levels and FAK/paxillin/Src/AKT/Erk signaling cannot explain the differential tumor growth generated by the MDA-MB-231 cells expressing the various GFP-LIMK1 fusions." (PMID 21682918, 2011). "On the contrary, other reports state that paxillin overexpression is a marker of a less invasive tumor phenotype in breast and lung carcinomas." (PMID 18492274, 2008). "Paxillin and kindlin are essential regulators of cell adhesion, signaling, and tumor progression." (PMID 40001476, 2025). "THL has been shown to inhibit adhesion to vitronectin and tumor-induced angiogenesis in vivo by decreasing paxillin in human umbilical vein endothelial cells (HUVECs); and to block Hsp27 phosphorylation by inducing endothelial cell adhesion and wound/tumor-driven angiogenesis in vitro." (PMID 41035918, 2025). "In addition, paxillin phosphorylation regulates other signaling molecules related to the tumor microenvironment, further enhancing the invasive capacity of the tumor." (PMID 40001476, 2025). "Phosphorylated paxillin strengthens FAs, enhancing the connection between tumor cells and ECM." (PMID 40001476, 2025). "Moreover, paxillin also enhances tumor cell proliferation and survival by regulating the PI3K/Akt and MAPK signaling pathways." (PMID 40001476, 2025). "Investigating paxillin’s potential regulation of β-catenin could provide insights into its role in cell fate determination and tumor progression." (PMID 40001476, 2025). "In particular, the increase in paxillin expression on both substrate for the tumor line may be beneficial as it corresponds to more structured FAs, thereby resulting in reduced motility rates." (PMID 38903185, 2024). "While EMT causes a decrease in epithelial, transmembrane glycoprotein E-cadherin, it causes an increase in mesenchymal, filamentary protein vimentin as well as Snail, Slug and regulatory adhesion adapter protein paxillin, which is also an EMT-associated tumor cell plasticity marker." (PMID 38190940, 2024).
tumor (continued). "As a result, dysadherin expression was higher in stage III CRC tissue than in stage II CRC tissue, and p-paxillin expression was high in tumor tissue with high dysadherin expression, while p-paxillin expression was low in tumor tissue with low dysadherin expression." (PMID 38725858, 2024). "Paxillin plays a regulatory role in diverse biological functions, including tumour migration, heterotypic adhesion, invasion, survival, and angiogenesis, contributing to the malignant development of tumours through various molecular mechanisms." (PMID 38500921, 2024). "In this review, we will briefly introduce the expression of paxillin in human cancer, its prognostic value, and how it affects malignant tumor progression and molecular mechanism, as well as the evidence contributing towards its potential to be used as a therapeutic target." (PMID 37175948, 2023). "Conversely, paxillin upregulation enhances several pro-proliferative pathways, such as CyclinD/Rb/E2F and DNA replication/repair pathways, which contribute to the abnormal proliferation of tumor cells." (PMID 37175948, 2023). "In a next step, we investigated whether inhibition of the paxillin-Src-Erk signalosome has effects on cancer cell migration toward neurons and tumor severity." (PMID 37607005, 2023). "This will fully unleash the potential role of paxillin as a tumor therapy target in the future." (PMID 37175948, 2023). "Not surprisingly, the low expression of FAK, paxillin, vinculin, and cortactin predicts good survival outcomes, considering that several studies report an association between their overexpression and tumor aggressiveness." (PMID 37686651, 2023). "However, as an inhibitor of VM in gallbladder cancer, norcantharidin can block the EphA2/FAK/paxillin signaling pathway to inhibit tumor VM formation." (PMID 37175948, 2023). "The potential tumor therapeutic drugs of targeting paxillin and its signaling pathway." (PMID 37175948, 2023). "Overall, these results also suggested that p-paxillin is a prognostic factor and may predict poor prognosis and aggressive tumor biology in human PDAC." (PMID 37607005, 2023). "The up-regulated expression of Mmps genes and down-regulated expression of focal adhesion genes including Talin, paxillin, vinculin, and Src, in tumor hybrid cells, indicated a greater ability of hybrid cells to detach from the tumor tissue and form distant metastasis." (PMID 37138326, 2023). "As the main component of focal adhesions, PXN might improve the adhesive abilities of cancer cells toward the nearby stroma and matrix, hence contributing to tumor adhesion and migration." (PMID 36923874, 2023). "Inhibition of paxillin-Src-Erk signalosome reduces NI, innervation, and tumor size." (PMID 37607005, 2023). "Though the prospect of gene therapy is broad, there are few tumor gene therapy drugs for paxillin, and the gene therapy drugs developed for paxillin may become a potential treatment approach in the future." (PMID 37175948, 2023). "Therefore, we believe that the TGF-α-CCL2-CCR4-p-paxillin axis is a clinically actionable target for constraining NI and tumor progression in PDAC." (PMID 37607005, 2023). "According to our results, regulation of microenvironment stiffness might provide a new strategy for tumor therapy and paxillin was the upstream of N-cadherin/β-catenin in this mechanotransduction process." (PMID 36683745, 2023). "Besides, the abnormal PXN expression would affect the ability of T cells in lysing tumor cells and in releasing the anti-tumor cytokine INFγ." (PMID 36923874, 2023). "Besides, upregulated PXN expression was observed in gastric cancer, and its abnormal expression correlated with tumor progression and poor prognosis." (PMID 36923874, 2023). "Therefore, the malignant phenotypes of tumor cells were suppressed by using siRNA for knockdown of p130Cas and paxillin, indicating that paxillin participated in the invasion of cells and that p130Cas participated in the growth and invasion of cells." (PMID 36824365, 2023).
tumor (continued). "Disrupting CCR4 or paxillin activity limited NI and dampened tumor size and tumor innervation." (PMID 37607005, 2023). "Additionally, a higher paxillin expression is generally associated with poorer overall survival and disease-free survival, suggesting that paxillin has multiple regulatory mechanisms in different tumor types." (PMID 37175948, 2023). "Overexpression of miRNA-5703 or knockdown of SRC inhibited the expression of paxillin, which suggests that this may be the mechanism by which miRNA-5703 in inhibits tumour metastasis (P < 0.05, or P < 0.01)." (PMID 34976193, 2022). "Due to early studies revealing that FAK acts as strong contributor to the cancer hallmarks in various human cancers, it was activated by integrins; interaction with paxillin resulted in focal adhesion formation and cytoskeleton remodeling promoted tumor invasion and metastasis." (PMID 35406599, 2022). "The expression levels of SphK1 and paxillin were significantly relevant to tumor pathological stage, presence of lymphatic metastasis, and development of distant metastasis, moreover, the expression of paxillin is closely correlated with the expression of SphK1 in CRC tissues." (PMID 34268882, 2021). "Analysis showed that aberrant expression of PXN was detected in 20 types of tumor tissues." (PMID 34135128, 2021). "In addition, these data provided the landscape of comprehensive features of PXN in pan-cancer tumor types." (PMID 34135128, 2021). "Therefore, it would be informative to investigate the effect of endothelial deletion of paxillin in tumour vascular permeability and metastasis." (PMID 33573141, 2021). "In addition, we also found that the tumor suppressor miR-145-5p downregulated the VEGF-A–induced expression of PXN in HUVECs." (PMID 34424263, 2021). "Further investigation of FA turnover and Paxillin degradation on tumor cell migration/metastasis in a dose and situation-dependent manner might better elucidate the detailed molecular mechanisms." (PMID 34654797, 2021). "KEGG pathways analysis indicated that regulation of the actin cytoskeleton and focal adhesions might play important roles in connecting PXN with tumor initiation and progression." (PMID 34135128, 2021). "Paxillin signaling is involved in cancer initiation and tumor cell dissemination and survival." (PMID 33244099, 2020). "ERK could facilitate tumor cell migration via phosphorylating calpain, myosin light chain kinase, paxillin, and focal adhesion kinase." (PMID 32760221, 2020). "However, Src-induced phosphorylation of PXN at Tyr38 increases the dasatinib resistance of tumor cells by activating the p130cas/PI3K/AKT signaling pathway." (PMID 32456226, 2020). "Moreover, GD3‐positive cells activate paxillin, p130Cas, and focal adhesion kinase, promoting tumor cell growth, and invasion." (PMID 32358995, 2020). "Pathologically, paxillin was identified in tumor nests and the neighboring area (Fig. 6b1–b3), supporting that paxillin expression could correlate with metastatic potential." (PMID 29855336, 2018). "Conversely, there are a greater proportion of liver metastases in the low paxillin pY88 cohort, suggesting that tumor microenvironment may modulate paxillin Y88 phosphorylation." (PMID 27447856, 2017). "Recent evidence on this matter shows that nuclear paxillin promotes DNA synthesis and proliferation, and also suppresses H19 gene expression, which is a parental imprinting gene hypothesized to be a tumor supressor." (PMID 28214467, 2017). "Paxillin localizes at focal adhesion contact and acts as a scaffold molecule providing a platform for FAK and Src, which are involved in cell migration events associated with tumor metastasis." (PMID 29234409, 2017). "Also, our previous immunohistochemistry study demonstrated that higher expressions of JNK/p-JNK and Paxillin/p-Paxillin S178 in tumor tissues were found when compared with those in the paracarcinoma tissue." (PMID 29088796, 2017).